IL6 (interleukin 6)
Diseases named in the same sentence as IL6 in open-access papers (continued):
Sharing a sentence is not in itself a finding about the gene and the disease.
tumor (continued). "In contrast, Th2 responses, associated with cytokines IL-4, IL-5, IL-6, and IL-10, suppress Th1 activity and may anergize effector T cells to tumor antigens." (PMID 26605345, 2015). "Serum IL-6 was shown as an independent risk factor for tumour recurrence." (PMID 25858079, 2015). "The relatively high level of IL-6 in non-tumor tissues might be caused by the infiltration of inflammatory cells." (PMID 26547929, 2015). "Serum IL-6, cancer site and type of therapy were significant risk factors for tumour recurrence." (PMID 25858079, 2015). "IL-6-deficient mice are resistant to multiple myeloma, while neutralization of TNFα switches inflammation-driven metastatic growth to inflammation-induced tumour regression." (PMID 25961014, 2015). "Therefore, association of IL-6 expression with histopathologic tumor response to chemoradiotherapy was examined in the patients with locoregionally advanced OSCC treated by the preoperative chemoradiotherapy with S-1." (PMID 25761055, 2015). "The IL-6 levels were induced by peritumoral hypoxia and associated with large tumor sizes." (PMID 26525581, 2015). "As for BrafV600E cells, COX-deficiency was associated with a shift in the inflammatory profile at the tumor site, with reduced expression of tumor promoting factors, such as Il6 or Il1b and increased levels of mediators associated with anti-tumor immune pathways." (PMID 26343581, 2015). "Overall, these results suggest that miR-21 signaling sustains EMT in these cancer cells to cause tumor progression and therapy resistance, and may affect the tumor immune microenvironment by activating IL-6 signaling." (PMID 26452030, 2015). "In addition to the inflammatory response, IL-6 has also been shown to be associated with various biological behaviors of tumor cells, including growth, survival, metastasis, angiogenesis, epithelial-mesenchymal transformation (EMT) and chemoresistance." (PMID 25609203, 2015). "If Any C-carriers with ER-negative tumours have an increased level of IL-6, an associated increase in NF-κβ may explain the impaired prognosis among those patients." (PMID 25305747, 2014). "Repressed TNF-α and IL-6 inhibit tumor growth in experimental models of colitis-associated cancer." (PMID 24766737, 2014). "In addition, a high NLR was associated with a high infiltration of tumor-associated macrophages (TAMs), TAMs promote systemic neutrophilia via secreting cytokines such as IL-6 and IL-8." (PMID 24559042, 2014). "IL-6 is associated with tumor progression in vivo and in clinical patients for certain cancers." (PMID 25238263, 2014). "Thus, by stimulation of DKK-1 expression in tumor cells, IL-6 inhibits Wnt-mediated osteogenesis, causing an imbalance in bone homeostasis and increased bone degradation." (PMID 25147739, 2014). "Several recent reports have implicated IL-6 as an important modulator of tumor progression." (PMID 24658029, 2014). "A study has shown that tumour growth caused by tobacco smoke was mediated by IL-6 and TNF-α." (PMID 26316944, 2014). "Moreover, ample clinical studies have implicated that higher serum IL-6 concentrations in cancer patients are associated with advanced tumor stages and poor survival." (PMID 24664372, 2014). "Similarly, the present study documented an association between IL-6 levels, tumor size and histological grading." (PMID 25120668, 2014). "Genetic ablation of IL-6 in mice has been shown to suppress both tumor growth and weight loss in an experimental cachexia model, implying that host-derived cytokines also could be considered as therapeutic targets." (PMID 24787299, 2014). "Carriers of genetic variants that up-regulate IL-6 and sIL-6R secretion may represent sub-groups of patients with a host-related feature that favors tumor growth, metastatic spread and cancer cachexia." (PMID 24886605, 2014). "As in residual cells, the role of Il-6/Stat3 in tumor dissemination may be linked to activation of cell growth and survival pathways." (PMID 23520493, 2013).
tumor (continued). "Additionally, TLR4 and IL-6 expression in the tumor microenvironment were associated with the presence of adenocarcinoma, and higher levels of TLR4 expression in the tumor stroma were noted with disease progression." (PMID 23650534, 2013). "Thus, IL-6 signaling has been linked to tumor aggressiveness, including cancer stem cell phenotypes and EMT phenotypes, drug resistance, and anoikis resistance, that is, contact-independent survival, which is required for travel through the vascular system." (PMID 24021059, 2013). "Altogether, these data point to different tumor-associated factors (i.e., IL-10, IL-6, PGE2) exerting their suppressive effects at various stages of myeloid DC development through converging and communicating signaling elements encompassing the JAK2/STAT3 and p38-MAPK pathways." (PMID 24324467, 2013). "To prove this hypothesis, we investigated the effect of curcumin, an inhibitor of IL-6 production, on vaccination of a highly attenuated Listeria monocytogenes (Listeriaat), encoding tumor-associated antigens (TAA) Mage-b in a TNBC model 4T1." (PMID 24156030, 2013). "We also found that IL-6 secreted by tumor-associated fibroblasts could upregulate STAT3 activation in NPC cells in culture." (PMID 24380387, 2013). "IL-6 has been implicated in regulating the expression of HIF-1 in some tumor cells." (PMID 24194900, 2013). "Alternatively, IL-17 has been shown to induce IL-6 production from tumor cells and tumor-associated stromal cells, which in turn activate STAT-3, an oncogenic transcription factor that upregulates pro-survival and pro-angiogenic gene levels in transformed cells." (PMID 23533029, 2013). "Besides tumor IL-6 silencing associates with a decrease in serum IL-6 (approx. 70% less in mice bearing lung or liver metastases)." (PMID 23517603, 2013). "Furthermore, positive staining for IL-6 was associated with higher tumor stage, higher rates of tumor recurrence and distant metastasis." (PMID 23561329, 2013). "As in our case, we did not examine the expression of G-CSF receptors and IL-6 receptors; therefore, it is really unknown whether G-CSF and IL-6 are associated with the proliferation of tumor cells." (PMID 23710188, 2013). "For example, TNF as well IL-1 and IL-6 are inducible by hypoxia, a hallmark of tumor cells." (PMID 25437036, 2013). "IL-6 inhibition was also associated with attenuated angiogenesis in tumor-bearing mice." (PMID 23561329, 2013). "Therefore, we suggest that IL-6 inhibition attenuates tumor regrowth after irradiation, an effect associated with decreased cell proliferation and attenuation of angiogenesis." (PMID 23806095, 2013). "Thus, high IL-6 serum levels are associated with lower survival, and at later stages, IL-6 can contribute to tumor growth progression." (PMID 23552194, 2013). "IL-6 signaling has been implicated in regulation of tumor growth and metastatic spread, and its level could be correlated with poor prognosis in different cancers." (PMID 23637926, 2013). "High IL6 expression in tumor cells was therefore significantly associated with aggressive clinical manifestations and might be an independent survival predictor, particularly in male OSCC patients." (PMID 23185547, 2012). "Furthermore, IL-6 has been shown to play a pathogenic role in the development and progression of several tumor types." (PMID 22236378, 2012). "The platelet decrease might reflect the therapeutic effects caused by the virus, reducing the amount of viable (hyper-IL-6 producing) tumor cells." (PMID 22236378, 2012). "Therefore there can be a possible causative role of tumor-derived IL-6 and abnormal values in hemoglobin and platelet levels, which have been recognized as prognostic factors." (PMID 22577583, 2012). "Increase in STAT3 signal fitness through oncogenic events and/or tumor-associated extrinsic signals such as IL-6 may be partially driven through APE1." (PMID 23094050, 2012).
tumor (continued). "Notably, administration of hyper-IL-6 abrogated protection from tumor progression in NFATc2-deficient mice and restored tumor incidence to levels observed in wild-type mice." (PMID 23109839, 2012). "High serum IL6 expression was also associated with age, smoking status, and tumor stage." (PMID 23185547, 2012). "Moreover, in these patients, there was a clear correlation between disease stage and performance status with markers of inflammation, such as IL-6 whereas low leptin levels were more closely associated with tumor stage and IL-6 levels than BMI." (PMID 22518191, 2012). "When IL6 expression was classified using a 2-tier grading system, high IL6 expression in tumor cells was significantly associated with a high rate of lymph node metastasis (P = 0.007) and poor tumor differentiation (P = 0.008)." (PMID 23185547, 2012). "In conclusion, in the CRC patients, raised serum VEGF and IL-6 may prove valuable non-invasive diagnostic indicators associated with advanced clinical stage and tumor metastasis that warrants further investigations." (PMID 21546718, 2011). "As observed for PDT-treated tumor cell lines, Cxcl2, Cxcl3 and Il6 were among the most strongly upregulated genes, although we cannot exclude that these cytokines were expressed by stromal cells in the tumor microenvironment or tumor-associated immune cells." (PMID 21738796, 2011). "Studies have shown that this drug causes a decrease in the normal cells’ production of the proinflammatory chemokine (C-C motif) ligand 2 (CCL2), which recruits monocytes to the tumor sites, and a decrease of interleukin-6 (a growth factor implicated in several malignancies), and VEGF." (PMID 22113577, 2011). "We understand that this proposed mechanism could be just one of the many plausible scenarios explaining resistance to EGFR-targeted therapies since alternative escape routes such as TGF-β and IL-6 axis have been implicated in other tumour types." (PMID 21792199, 2011). "In this last context, it is interesting that both in vivo and in vitro studies indicate that IL-6 produced by stromal tumor associated fibroblasts also enhances OC cell proliferation through activated signal transducer and activator of transcription 3 (STAT3) signaling." (PMID 21765834, 2011). "In CRC patients, preoperative measurement of serum VEGF and Il-6 may prove useful non-invasive diagnostic indicators associated with advanced clinical stage and tumor metastasis that warrants further investigations." (PMID 21546718, 2011). "Interestingly, positive IL-6 immunohistochemical reactivity in the cytoplasm of tumour cells was significantly associated with reduced tumoral expression of sIL-6R." (PMID 20823887, 2010). "Importantly, IL-6 promotes tumor progression in inflammation-associated tumor models through the activation of STAT3." (PMID 20885960, 2010). "Furthermore, IL-6 expression was localised within the tumour, suggesting that the tumour or its associated stroma was the source of the increased circulating IL-6 noted in this model." (PMID 19450285, 2009). "This could be the consequence of acquisition of mutations during tumour development and progression, or, respectively, caused by specific polymorphisms in the IL-6 promoter." (PMID 18205904, 2008). "Furthermore, our findings suggest an association between circulating IL-6 levels and the upregulation of multidrug resistance genes within the tumour." (PMID 18059400, 2008). "It is therefore unclear whether elevated serum levels of IL-6 are a consequence of or a contributory cause to advanced tumour stage." (PMID 14735187, 2004). "Expression of IL-6 was associated with tumours that expressed ≥ 3 steroid-converting enzymes." (PMID 10574257, 1999). "Moreover, IL‐6 has been associated with malignancy in thyroid nodules and tumor invasiveness." (PMID 40620232, 2025).
tumor (continued). "Notably, the correlative immune analysis showed that Hsp90 inhibition changed the tumor immune profile, with decreases in IL-6-producing cells and tumor-associated macrophages and system-wide increases in inflammatory cytokines, which implies enhanced immune activation." (PMID 40732313, 2025). "Taking into consideration that elevated levels of IL-6 are associated with tumor growth, as well as elevated levels of VEGF being associated with angiogenesis stimulation, the observed impact of propolis on these cytokines demonstrates that propolis may potentially inhibit tumor progression." (PMID 40143164, 2025). "Therefore, an elevated IL-10/IL-6 serum ratio may help exclude patients with underlying systemic infection or inflammation, thereby improving specificity for tumor-associated cytokine imbalances." (PMID 40881684, 2025). "Blocking IL-6 could reverse the tumor-promoting effect caused by cSERPINE2 overexpression." (PMID 40443670, 2025). "Notably, reduced 5-HT levels have been linked to increased TNF-α and IL-6, creating a feed-forward loop between neurotransmitter imbalance and inflammation that may foster a microenvironment conducive to tumor growth and metastasis." (PMID 41480347, 2025). "Factors such as impaired liver function, chronic liver inflammation, fibrosis, cirrhosis, increased systemic inflammation, tumor-associated cytokines (e.g., IL-6, TNF-α), tumor hypoxia, and elevated VWF levels in HCC may also contribute to a relative deficiency of ADAMTS13." (PMID 40699668, 2025). "Interestingly, interleukin-6 (IL-6)/STAT3 signaling has also been implicated in EMT within tumor-infiltrating myeloid cells (TIMs), CAFs, and tumor-associated adipocytes, suggesting that STAT3/IL-6 pathways may jointly participate in GPR81-mediated EMT." (PMID 40948941, 2025). "Cytokines such as IL-6 released by tumor cells may cause astrocyte activation." (PMID 40149331, 2025). "These mutations increase EGFR amplification and interleukin 6 (IL-6) levels, inducing angiogenesis and tumor necrosis, and decrease glycogen accumulation, limiting glucose oxidation, nucleic acid and de novo fatty acid synthesis, and promoting tumor cell apoptosis." (PMID 41007844, 2025). "In MM, BCL6 might underwent abnormal reactivation, particularly in specific subtypes such as those with low CD138 expression or IL-6-dependent cells, where heightened expression was intimately linked to tumor cell proliferation, survival, and resistance to treatment." (PMID 41357603, 2025). "In addition, the damage-associated molecular patterns (DAMPs) released by tumor cells after being killed by particles can activate macrophages and neutrophils, leading to abnormal upregulation of inflammatory factors such as IL-1β, IL-6, and TNF-α." (PMID 40740952, 2025). "Moreover, the UPR activates the secretion of pro-inflammatory cytokines and chemokines, such as IL-6 and IL-8, which promote local chronic inflammation and promote the recruitment of immune cells with pro-tumor phenotypes, such as tumor-associated macrophages with immunosuppressive characteristics." (PMID 40278350, 2025). "Therefore, it is unclear whether recipients with donor rs1800796 CC genotypes, which are associated with tumor relapse, secrete lower amounts of IL6." (PMID 39860482, 2025). "Furthermore, IL-6 has been clinically associated with poor prognosis in cSCC, thereby underscoring the critical involvement of inflammatory molecules in tumor progression." (PMID 40296873, 2025). "In parallel, HPV-related lesions exhibit cytokine and chemokine programs (including IL-6/IL-8 and other myeloid-recruiting signals) that support expansion and recruitment of suppressive myeloid compartments, including tumor-associated macrophages (TAMs) and tumor-associated neutrophils (TANs)." (PMID 41516306, 2025). "Furthermore, IL-6 has been implicated in tumor progression, angiogenesis, and immunosuppression." (PMID 39336572, 2024).
tumor (continued). "M1 macrophages could produce inflammatory cytokines such as interleukin (IL)‐6 and IL‐1β, killing tumour cells and pathogenic microorganisms whereas M2 macrophages secret growth factors such as epidermal growth factor (EGF) participating in the tissue remodelling or tumour progression." (PMID 38680032, 2024). "However, our group has recently challenged active IL-6/STAT3 signaling as a tumor driver in PCa, as loss of Stat3 unexpectedly resulted in increased tumor burden and was accompanied by a bypass of PTEN-loss induced cellular senescence (PICS) in a Pten-deficient PCa mouse model." (PMID 38811984, 2024). "Furthermore, inflammatory cytokines, such as TNF-α, IL-1, and IL-6; growth factors; chemokines; and proteases secreted by tumor-associated lymphocytes and macrophages increase tumor cell proliferation, survival, migration, and invasion, thus promoting tumor growth and metastasis." (PMID 38297164, 2024). "Moreover, IL6 from tumor-associated macrophages (TAMs) activates the JAK/STAT3 pathway, leading to transcriptional inhibition of tumor suppressors, while caspase-related IL-8 is considerably related to the recruitment of anti-inflammation macrophage through neutrophil." (PMID 38844562, 2024). "Furthermore, IL-6 is considered a pivotal tumor promoter in colitis-associated cancer." (PMID 38592255, 2024). "Furthermore, S100A7 could facilitate the secretion of immunomodulators, including IL-6, in tumors and tumor-associated immune cells, thereby enhancing tumor infiltration." (PMID 38499391, 2024). "Furthermore, IL-6 attracts the immune-suppressive M2 macrophages and stimulates fibroblast differentiation into cancer-associated fibroblasts (CAFs) with a myofibroblast phenotype, thus shaping tumor microenvironment (TME)." (PMID 38715108, 2024). "Moreover, it induces high-density neutrophil enrichment by secreting the IL-8 family of cytokines and recruits several myeloid-derived suppressor cells by producing chemokines, such as IL-6, eventually causing the formation of a cold tumor immune microenvironment." (PMID 38632512, 2024). "Thus, the observed modulation of IL-8 and IL-6 signaling by STING loss suggests that STING activation may limit tumor-promoting effects of senescence and SASP." (PMID 38900577, 2024). "IL-6/STAT3 tumor stemness may be associated with elevated reactive oxygen species (ROS) levels." (PMID 39092186, 2024). "Reduced IL-1β, IL-6, and IL-8 concentrations in the salivary supernatant fluid of patients with cancerReduction in Bacteroidetes species in cancer subjectsUp-regulation of genes associated with differentiation and T-cell recruitment to the tumor microenvironment." (PMID 37892459, 2023). "Tumour infiltrating immune cells including T cells can also be affected by cancer-associated fibroblasts that can promote tumour growth and prevent and polarize T-cell function through the release of cytokines and chemokines such as TGFβ, IL6, indoleamine 2,3-dioxygenase (IDO), and CXCL12." (PMID 38567060, 2023). "We hypothesized that IL-6 levels might be associated with the state of anti-tumor immunity related to the treatment effect of eribulin, and so we analyzed the peripheral blood fractions for helper (CD4+) and cytotoxic (CD8+) lymphocytes, Tregs and MDSCs involved in tumor immunity at baseline." (PMID 37733188, 2023). "Thus, our data demonstrate that Q11 can improve the tumor microenvironment by attenuating oxidative damage and inhibiting the inflammatory response, which may be associated with the IL‐6/STAT3 pathway and the MAPK/ERK pathway." (PMID 37875398, 2023). "Our data demonstrated an anti-inflammatory action on tumor cells due to the association of CrataBL and its related peptides with vemurafenib because NO production was significantly reduced, as well as the inflammatory cytokines IL-6 (30%, 24 h), IL-8, and PDGF-AB/BB." (PMID 37445794, 2023).